RAB11FIP2 (RAB11 family interacting protein 2)
Description:
A Rab11 effector binding preferentially phosphatidylinositol 3,4,5-trisphosphate (PtdInsP3) and phosphatidic acid (PA) and acting in the regulation of the transport of vesicles from the endosomal recycling compartment (ERC) to the plasma membrane. Involved in insulin granule exocytosis. Also involved in receptor-mediated endocytosis and membrane trafficking of recycling endosomes, probably originating from clathrin-coated vesicles. Required in a complex with MYO5B and RAB11 for the transport of NPC1L1 to the plasma membrane. Also acts as a regulator of cell polarity. Plays an essential role in phagocytosis through a mechanism involving TICAM2, RAC1 and CDC42 Rho GTPases for controlling actin-dynamics.
Synonyms: Rab11-FIP2; KIAA0941; nRip11
Tractability: Small molecule: a structure with a bound ligand is known. Antibody: UniProt places it where antibodies can reach, with medium confidence; its Gene Ontology location is reachable by antibodies, with medium confidence. PROTAC: ubiquitination databases record sites on it; its protein half-life has been measured.
Gene: Protein-coding gene on chromosome 10 (118,004,916 to 118,046,941, reverse strand). Ensembl gene ENSG00000107560.
Subcellular location: Cell projection, phagocytic cup; Cell membrane; Recycling endosome membrane
Subcellular location (Human Protein Atlas): Vesicles; Nucleoplasm
Pathways (Reactome):
Transport of small molecules: Vasopressin regulates renal water homeostasis via Aquaporins
Gene Ontology:
Molecular function: identical protein binding; protein binding; protein homodimerization activity; protein kinase binding; small GTPase binding
Biological process: establishment of cell polarity; phagocytosis; positive regulation of GTPase activity; TRAM-dependent toll-like receptor 4 signaling pathway; insulin secretion involved in cellular response to glucose stimulus; regulated exocytosis; cell communication; positive regulation of protein localization to plasma membrane; signaling; vesicle-mediated transport
Cellular component: endosome; phagocytic cup; cytoplasmic vesicle membrane; plasma membrane; recycling endosome membrane
Genetic constraint (gnomAD): Loss-of-function variants: 10 observed, 35.14 expected, observed/expected ratio (o/e) 0.28, 90% interval 0.17 to 0.48. The upper end of that interval is the gene's LOEUF score, 0.48, which puts it in group 2 of 6, group 1 being the genes least tolerant of losing a copy. Missense variants: 503 observed, 599.19 expected, observed/expected ratio (o/e) 0.84, 90% interval 0.78 to 0.9. Synonymous variants: 218 observed, 215.56 expected, observed/expected ratio (o/e) 1.01, 90% interval 0.9 to 1.13.
Homologues: Orthologues: chimpanzee RAB11FIP2 (99% identical), dog RAB11FIP2 (95% identical), guinea pig RAB11FIP2 (95% identical), macaque RAB11FIP2 (94% identical), pig RAB11FIP2 (94% identical), mouse Rab11fip2 (93% identical), rat Rab11fip2 (93% identical), rabbit RAB11FIP2 (92% identical), tropical clawed frog rab11fip2 (60% identical), zebrafish rab11fip2 (53% identical), Drosophila melanogaster Rip11 (28% identical), Caenorhabditis elegans rfip-2 (15% identical). Paralogues in human: RAB11FIP1 (42% identical), RAB11FIP5 (34% identical).
Diseases named in the same sentence as RAB11FIP2 in open-access papers:
RAB11FIP2 is named in the same sentence as 8 diseases in open-access papers, as found by Europe PMC text mining. Sharing a sentence is not in itself a finding about the gene and the disease. The quoted sentences say what the papers report.
colorectal cancer (3 papers, 2022 to 2023). A primary or metastatic malignant neoplasm that affects the colon or rectum. "Moreover, an overexpression of the Rab11 family-interacting protein 2 (Rab11-FIP2) in colorectal cancer patients was correlated with increased angiogenesis, tumor migration and consequent metastasis formation." (PMID 36986603, 2023). "Similarly, RAB11FIP2 regulates actin dynamics and has been shown to contribute to metastasis in colorectal cancer." (PMID 35336722, 2022).
gastric cancer (1 paper, 2019). A primary or metastatic malignant neoplasm involving the stomach. "RAB11FIP2, a member of the RAB11 family of interacting proteins, exhibited potential tumor suppressor function since blocking of the miR-192/215-RAB11FIP2 axis could inhibit gastric cancer progression." (PMID 30837324, 2019).
tumor (4 papers, 2019 to 2023). "RAB11 family interacting protein 2 (RAB11FIP2), as a conserved protein and effector molecule for the small GTPase Rab11, is found to play important roles in tumor progression and metastasis." (PMID 37344885, 2023). "RAB11FIP2 is a member of the RAB11 family interacting proteins (RAB11-FIP) that plays crucial roles in tumour growth and metastasis." (PMID 33937069, 2021).
RAB11FIP2 also shares sentences with these, for which no sentence is quoted: breast carcinoma (1 paper); cancer (1); melanoma (1); syndrome of Lowe (1); trigonocephaly (1).